COQ2 (coenzyme Q2, polyprenyltransferase)
Description:
Mediates the second step in the final reaction sequence of coenzyme Q (CoQ) biosynthesis. Catalyzes the prenylation of para-hydroxybenzoate (PHB) with an all-trans polyprenyl donor (such as all-trans-decaprenyl diphosphate). The length of the polyprenyl side chain varies depending on the species, in humans, the side chain is comprised of 10 isoprenyls (decaprenyl) producing CoQ10 (also known as ubiquinone), whereas rodents predominantly generate CoQ9. However, this specificity is not complete, human tissues have low amounts of CoQ9 and rodent organs contain some CoQ10. Plays a central role in the biosynthesis of CoQ10. CoQ10 is a vital molecule that transports electrons from mitochondrial respiratory chain complexes. CoQs also function as cofactors for uncoupling protein and play a role as regulators of the extracellularly-induced ceramide-dependent apoptotic pathway. Regulates mitochondrial permeability transition pore (mPTP) opening and ROS production (pivotal events in cell death) in a tissue specific manner (By similarity).
Synonyms: PHB:PPT; CL640; FLJ26072; COQ10D1; MSA1
Tractability: Antibody: UniProt predicts a signal peptide or a membrane-spanning region. PROTAC: ubiquitination databases record sites on it.
Safety:
Unwanted effects reported when the protein is acted on. In parentheses: how it was acted on, where the effect was seen, and who reports it.
statin intolerance (source: ClinPGx)
statin-related muscle symptoms (source: ClinPGx)
Gene: Protein-coding gene on chromosome 4 (83,261,536 to 83,284,914, reverse strand). Ensembl gene ENSG00000173085.
Subcellular location: Mitochondrion inner membrane
Subcellular location (Human Protein Atlas): Cytosol
Pathways (Reactome):
Metabolism: Ubiquinol biosynthesis
Protein localization: Mitochondrial protein import
Gene Ontology:
Molecular function: 4-hydroxybenzoate polyprenyltransferase activity; prenyltransferase activity; transferase activity, transferring alkyl or aryl (other than methyl) groups
Biological process: glycerol metabolic process; ubiquinone biosynthetic process; isoprenoid biosynthetic process
Cellular component: mitochondrial inner membrane; mitochondrion; extrinsic component of mitochondrial inner membrane; membrane
Genetic constraint (gnomAD): Loss-of-function variants: 16 observed, 23.55 expected, observed/expected ratio (o/e) 0.68, 90% interval 0.46 to 1.03. The upper end of that interval is the gene's LOEUF score, 1.03, which puts it in group 4 of 6, group 1 being the genes least tolerant of losing a copy. Missense variants: 418 observed, 354.37 expected, observed/expected ratio (o/e) 1.18, 90% interval 1.09 to 1.28. Synonymous variants: 179 observed, 144.39 expected, observed/expected ratio (o/e) 1.24, 90% interval 1.1 to 1.4.
Gene-disease validity (ClinGen):
ClinGen rates the evidence that COQ2 causes each of these diseases.
mitochondrial disease (autosomal recessive): Definitive.
Homologues: Orthologues: chimpanzee COQ2 (99% identical), macaque COQ2 (96% identical), pig COQ2 (85% identical), dog COQ2 (84% identical), rabbit COQ2 (84% identical), mouse Coq2 (80% identical), guinea pig COQ2 (78% identical), rat Coq2 (68% identical), zebrafish coq2 (64% identical), tropical clawed frog coq2 (63% identical), Drosophila melanogaster Coq2 (54% identical), Caenorhabditis elegans coq-2 (46% identical). Paralogues in human: COX10 (23% identical).
Diseases named in the same sentence as COQ2 in open-access papers:
COQ2 is named in the same sentence as 76 diseases in open-access papers, as found by Europe PMC text mining. Sharing a sentence is not in itself a finding about the gene and the disease. The quoted sentences say what the papers report.
multiple system atrophy (15 papers, 2014 to 2024). Multiple system atrophy (MSA) is a neurodegenerative disorder characterized by autonomic failure (cardiovascular and/or urinary), parkinsonism, cerebellar impairment and corticospinal signs with a median survival of 6-9 years. "A similar effect was described in patients with multiple system atrophy with altered biosynthesis of the electron carrier CoQ10 as a consequence of a mutation in the COQ2 gene." (PMID 31996177, 2020). "Multiple rare variants in COQ2 have been reported to be associated with multiple system atrophy by analyzing familial clustering." (PMID 28420387, 2017). "For example, multiple system atrophy was once thought to be sporadic, but recently-identified compound heterozygous and recessive mutations in COQ2 segregate with the disease, and heterozygous mutations in the same gene predispose individuals to this disease." (PMID 25773295, 2015). "Recently, recessive mutations of the COQ2 gene have been identified in two unrelated Japanese families with multiple system atrophy (MSA)." (PMID 25373618, 2014). "Moreover, COQ2 deficiency is a known cause of multiple system atrophy (MSA) in late adulthood (OMIM #146500)." (PMID 36978966, 2023). "The Multiple-System Atrophy Research Collaboration (MSARC) first published findings of a possible association between COQ2 and MSA after identifying a homozygous mutation (M128V-V393A/M128V-V393A) and compound heterozygous mutations (R387X/V393A) in COQ2 in two multiplex Japanese families." (PMID 36765380, 2023). "Mutations in the COQ2 gene lead to multiple system atrophy and cerebellar ataxia." (PMID 35159210, 2022). "Moreover, mutations in COQ2 have been recently reported in Japanese patients with multiple system atrophy." (PMID 25802402, 2015). "Mutations/variants of COQ2 have been found to modulate the risk of familial and sporadic multiple system atrophy (MSA) in Japan, supported by impaired COQ2 activities in affected subjects." (PMID 25977831, 2015). "Mutations in the COQ2 and COQ4 genes can lead to CoQ deficiency disorders such as multiple system atrophy and primary coenzyme Q10 deficiency, which often result in mitochondrial dysfunction and a wide range of symptoms, including muscle weakness, neurologic abnormalities, and cardiomyopathy." (PMID 38455045, 2024).
Nephropathy (10 papers, 2017 to 2025). A nonspecific term referring to disease or damage of the kidneys. "The primary CoQ10 deficiency caused by COQ2 defect is mostly manifested as encephalopathy, encephalopathy with nephropathy, and rarely as an isolated nephrotic syndrome." (PMID 33397173, 2021). "An association between CoQ2 mutation and renal disease was implied according to the genetic sequencing results." (PMID 33397173, 2021). "In this study, we identify two novel recessive variants in the COQ2 gene which, when acting together in the compound heterozygous state, result in primary CoQ10 deficiency with associated nephropathy and retinopathy." (PMID 33187544, 2020). "In 2007, scholars reported two cases of patients with early onset of glomerular lesions, and both cases have found COQ2 gene mutations; the study puts forward the concept of “COQ2 kidney disease”." (PMID 31660881, 2019). "The impact of CoQ2 gene mutations includes mitochondrial encephalomyopathy and nephropathy." (PMID 39803153, 2024). "COQ2 mutation‐related nephropathy was the first to be described, reported in 2005." (PMID 32685349, 2020). "Kidney diseases caused by COQ2 gene mutations can manifest as SRNS, with poor prognosis." (PMID 31660881, 2019). "COQ2 mutations (causing CoQ10 deficiency COQ10D1) typically manifest as encephalopathy and nephropathy of variable severity." (PMID 37627647, 2023). "Scholars reported a 33-month-old boy with infant brain myopathy, kidney disease and COQ10 deficiency, and a homozygous missense mutation was found in COQ2 genes after genetic testing." (PMID 31660881, 2019). "Mutations in the COQ2 gene can lead to coenzyme Q10 (COQ10) deficiency, a type of mitochondrial encephalomyopathy and kidney disease, an inherited mitochondrial disease that mainly affects the kidneys." (PMID 31660881, 2019). "In contrast to many other COQ2 pathogenic variant phenotypes described, the phenotype here does not exhibit neurologic manifestations, but rather severe nephropathy combined with retinopathy in multiple affected members of the family." (PMID 33187544, 2020). "Mutations in PDSS2 and COQ2 are also mostly associated with progressive encephalopathy, seizures, and hypertrophic cardiomyopathy, while ADCK4 disease typically manifests as an isolated nephropathy." (PMID 30232548, 2018).
primary coenzyme Q10 deficiency (8 papers, 2018 to 2024). "Coenzyme Q10 deficiency can result from pathogenic variants in the COQ2, COQ4, COQ6, COQ8A, or COQ8B gene." (PMID 38570878, 2024). "Pathogenic variants in any of the genes involved in the biosynthetic pathway of coenzyme Q10 can result in a primary CoQ10 deficiency phenotype; in particular, the genes COQ2 and PDSS2 have been associated with retinopathy and optic atrophy, respectively." (PMID 33187544, 2020). "Although there are several reports of COQ2 variants causing primary CoQ10 deficiency, only three of the reported patients with confirmed variants in the COQ2 gene with associated retinopathy have been reported in the literature." (PMID 33187544, 2020). "We present in this report a rare oculorenal syndrome in three related patients associated with novel compound heterozygous variants in the COQ2 gene, resulting in primary coenzyme Q10 deficiency that manifests primarily as retinitis pigmentosa and renal failure." (PMID 33187544, 2020). "The COQ2 gene was the first to be identified as a cause of primary CoQ10 deficiency when altered." (PMID 33187544, 2020). "For the first time, COQ2 gene coding mutations can lead to primary COQ10 deficiency." (PMID 31660881, 2019). "However, the child’s phenotype resembled that associated with loss of function of the COQ2 gene (primary coenzyme Q10 deficiency, OMIM #607426,)." (PMID 29373990, 2018). "Moreover, the spectrum of symptoms of encephalopathy, intellectual disability, seizures, and muscle involvement has been described in patients with variants responsible for other primary coenzyme Q10 deficiency (COQ2, COQ4, COQ6, COQ7, COQ9) as well as in patients with COQ8A-ataxia." (PMID 36295857, 2022).
cerebellar ataxia (7 papers, 2016 to 2024). A neurological syndrome characterized by clumsy and uncoordinated movement of the limbs, trunk, and cranial muscles. "It should be also emphasised that rare autosomal recessive disorder, CoQ10 deficiency (mutation in CABC1; COQ2; COQ9; PDSS1; PDSS2 genes), is frequently associated with seizures, cognitive decline, pyramidal track signs, myopathy, and prominent cerebellar ataxia." (PMID 29456787, 2017). "COQ2 variants have been associated with a syndrome resembling multiple-system atrophy (MSA), a non-monogenic neurodegenerative alpha synucleinopathy disorder characterized by autonomic failure in addition to various combinations of parkinsonism, cerebellar ataxia, and pyramidal dysfunction." (PMID 38673663, 2024).
nephrotic syndrome (5 papers, 2014 to 2025). A collection of symptoms that include severe edema, proteinuria, and hypoalbuminemia; it is indicative of renal dysfunction. "Treatment with CoQ10 supplementation in primary CoQ10 deficiency due to COQ2 mutations with isolated nephrotic syndrome has demonstrated promising results, including resolution of the nephrotic syndrome and restoration of normal kidney function." (PMID 39656276, 2025). "To date, more than 60 patients with COQ2 mutations have been reported, with phenotypes ranging from isolated nephrotic syndrome to multisystem disease." (PMID 39656276, 2025).
lactic acidosis (4 papers, 2019 to 2025). Metabolic acidosis characterized by the accumulation of lactate in the body. "In two patients with mutations in COQ2 gene, early treatment with CoQ10, initiated immediately after birth, led to the resolution of lactic acidosis and normalization of glucose levels in one patient, and improvement in proteinuria in the other." (PMID 39656276, 2025).
renal failure (4 papers, 2016 to 2025). "Two affected individuals carrying biallelic pathogenic variants in COQ2 were diagnosed with renal failure, which required renal transplantation." (PMID 36266294, 2022).
diabetes (3 papers, 2020 to 2026). "For complications in organs other than the kidney, hearing loss (66.7%) was the most common complication, followed by diabetes (48.2%) among all cases, whereas developmental disorders were frequently observed in patients with COQ2 mutation, COQ6 mutation, and mtDNA single deletion." (PMID 35257070, 2022).
glomerulopathy (3 papers, 2019 to 2022). "Mutations in genes related to coenzyme Q10, another mitochondrially associated antioxidant, including PDSS1, PDSS2, COQ2, COQ6, and COQ8B/ADCK4, are associated with the development of glomerular disease." (PMID 34874915, 2022). "We suggest treating the individuals with biallelic pathogenic variants in COQ2, COQ6, and PDSS2 or presenting phenotype suggestive of CoQ10-related glomerulopathy with oral CoQ10 as early as possible." (PMID 32467597, 2020). "We present the case of a 6-month-old girl with steroid-resistant glomerulopathy due to a COQ2 defect with no additional systemic symptoms." (PMID 31660881, 2019).
Parkinson disease (3 papers, 2015 to 2022). A progressive degenerative disorder of the central nervous system characterized by loss of dopamine producing neurons in the substantia nigra and the presence of Lewy bodies in the substantia nigra and locus coeruleus. "Summary of COQ2 variants genotyped by ligase detection reaction (LDR) in Han Chinese patients with Parkinson's disease." (PMID 26098829, 2015).
encephalomyopathy (2 papers, 2020). "Individuals with COQ2 mutations presented with phenotypes ranging from isolated NS to neonatal multisystem disorder with encephalomyopathy and renal involvement, as well as a recently described case of multiple‐system atrophy." (PMID 32685349, 2020).
epilepsy (2 papers, 2020 to 2024). A brain disorder characterized by episodes of abnormally increased neuronal discharge resulting in transient episodes of sensory or motor neurological dysfunction, or psychic dysfunction. "Primary CoQ deficiency was initially reported in association with COQ2 mutations, characterized by encephalopathy, cerebellar dysplasia, and epilepsy, with a seizure incidence of approximately 40%." (PMID 39850733, 2024).
periodontitis (2 papers, 2024 to 2026). An acute or chronic inflammatory process that affects the tissues that surround and support the teeth. "The expression trends of CFI (upregulated) and COQ2 (downregulated) were first confirmed in TNF-α/IL-1β-stimulated human periodontal ligament cells and further validated in a rat ligature-induced periodontitis model." (PMID 41998822, 2026).
anemia (1 paper, 2013). A reduction in the number of red blood cells, the amount of hemoglobin, and/or the volume of packed red blood cells. "The patients were comprehensively investigated for common etiologies of anemia, uric acid metabolism and mitochondrial metabolism, including sequencing of several genes (HNF1, UMOD, CoQ2, PDSS2 and partially the mtDNA) but no underlying cause was identified." (PMID 24034276, 2013).
coronary heart disease (1 paper, 2022). "COQ2 encodes a well-studied homolog of mitochondrial coenzyme Q oxidoreductases essential for mitochondrial function and is linked to the susceptibility of coronary heart disease." (PMID 36568976, 2022).
deficiencies (1 paper, 2023). "Primary COQ2 deficiencies may present with a wide spectrum of disease severity (primary coenzyme Q10 deficiency-1; COQ10D1; OMIM #607426)." (PMID 36978966, 2023). "This is a typical finding in adult-onset forms of COQ2, COQ4 and COQ8A deficiency." (PMID 36978966, 2023).
dementia (1 paper, 2015). Loss of intellectual abilities interfering with an individual's social and occupational functions. "We examined the role of COQ2 in patients with dementia and essential tremor (ET), two common neurodegenerative conditions." (PMID 25977831, 2015). "Since COQ2 is vital for redox balance in neurons and the role of COQ2 variants is unknown in other neurodegenerative diseases such as dementia and essential tremor, we conducted an association analysis of COQ2 variants in a cohort of dementia and essential tremor (ET) patients." (PMID 25977831, 2015). "COQ2 gene is unlikely to play a significant role in dementia and essential tremor in our population." (PMID 25977831, 2015). "COQ2 gene is unlikely to play a significant role in patients with dementia or ET in our population." (PMID 25977831, 2015).
Hyperglycemia (1 paper, 2025). An increased concentration of glucose in the blood. "Neonatal hyperglycemia has not been reported in any of these cases but has been described for two other Coenzyme Q10 disorders caused by variants in COQ2 and COQ4." (PMID 40062559, 2025).
Leukoencephalopathy (1 paper, 2023). This term describes abnormality of the white matter of the cerebrum resulting from damage to the myelin sheaths of nerve cells. "Another brain pathology observed in individuals with COQ defects is disturbed myelination and leukoencephalopathy (PDSS1, COQ2, COQ6, COQ7 and HPDL)." (PMID 36978966, 2023).
melanoma (1 paper, 2022). A malignant, usually aggressive tumor composed of atypical, neoplastic melanocytes. "Overall, we observed that COQ2 mRNA level is similarly expressed by melanocytes and other melanoma cells, except for IPC-298, SkMel3 and A375 where COQ2 mRNA is significantly upregulated." (PMID 35255427, 2022).
nephrosis (1 paper, 2009). Pathological processes of the KIDNEY without inflammatory or neoplastic components. "Patients with mutations in para-hydroxybenzoate-polyprenyl transferase (COQ2), a component of the CoQ10 biosynthesis complex which condenses the parahydroxybenozoate ring with the decaprenyl side-chain, share early-onset nephrosis and encephalophaty." (PMID 27713230, 2009).
neuropathy (1 paper, 2019). A disorder affecting the nervous system that manifests with pain, tingling, numbness, and/or muscle weakness. "We believe that if the onset age is early, homozygous mutation and/or neuropathy are the risk factors for the severe cases resulting from the COQ2 mutation." (PMID 31660881, 2019).
Obesity (1 paper, 2020). Accumulation of substantial excess body fat. "COQ2 (coenzyme Q2) and PLAC8 (placenta-specific 8) are candidate genes for the onset of type 2 diabetes associated with obesity in rats." (PMID 31940795, 2020).
optic atrophy (1 paper, 2025). A disorder characterized by loss of optic nerve fibers. "It is interesting to note that some patients with inherited pathogenic variants in genes implicated in primary CoQ10 deficiency manifest with optic atrophy as a feature of complex neurological phenotypes, including mutation of COQ1/PDSS1, COQ2 and COQ6." (PMID 40859035, 2025).
Optic neuropathy (1 paper, 2024). "We propose that the COQ2 mutations cause mitochondrial electron transfer system dysfunction, resulting in LHON-like optic neuropathy." (PMID 39271608, 2024).
Parkinsonism (1 paper, 2022). Characteristic neurologic anomaly resulting from degeneration of dopamine-generating cells in the substantia nigra, a region of the midbrain, characterized clinically by shaking, rigidity, slowness of movement and difficulty with walking and gait. "In addition, a recent study reported that, in rare cases, COQ2 variants are related to the onset of familial PD, suggesting that COQ2 variants might share similar pathways and be involved in induction of the phenotype of PD or parkinsonism." (PMID 36499400, 2022).
Pigmentary retinopathy (1 paper, 2020). An abnormality of the retina characterized by pigment deposition. "Why COQ2 is the only gene thus far to definitively cause pigmentary retinopathy remains to be determined." (PMID 33187544, 2020).